TLR2 (toll like receptor 2)
Diseases named in the same sentence as TLR2 in open-access papers (continued):
Sharing a sentence is not in itself a finding about the gene and the disease.
asthma (continued). "Consistent with this is a previous study in chronic persistent severe asthma (n = 9) which demonstrated increased mRNA expression of the innate immune receptors TLR2, TLR4 and CD14, as well as the cytokines IL-8 and IL-1β in induced sputum from patients with neutrophilic asthma." (PMID 24955983, 2014). "Numerous studies have implicated TLR2, TLR4 and TLR9 in the pathogenesis of asthma or atopy." (PMID 24524443, 2014). "In conclusion, we show that local TLR-2 activation at the time of allergen challenge results in slightly exacerbated asthma manifestations at the time of treatment, while rendering a long-lasting protection against AHR and allergic inflammation upon allergen provocation at later time points." (PMID 23393567, 2013). "We hypothesized that the TLR-2-driven expansion of Tregs could be employed to increase their activity in allergen sensitized mice resulting in reduced asthma manifestations upon subsequent allergen provocations." (PMID 23393567, 2013). "Therefore, we designed an adapted asthma protocol allowing us to circumvent the immediate pro-inflammatory effects of TLR-2 stimulation by Pam3Cys." (PMID 23393567, 2013). "This duality in the effects of TLR-2 activation may also explain some of the disparate results previously published concerning the role of TLR-2 in experimental asthma." (PMID 23393567, 2013). "Here, we aim to test whether long-term suppression of asthma manifestations can be achieved by locally expanding the Treg cell subset via intranasal administration of a TLR-2 agonist." (PMID 23393567, 2013). "TLR2, TLR6, TLR9, and TLR10 have been associated with asthma in several studies." (PMID 23496969, 2013). "In this study, we tested whether expansion of Treg cells via TLR-2 activation at the time of allergen challenge can result in long-term protection against asthma manifestations in the mouse." (PMID 23393567, 2013). "Altogether, stimulating TLR2 seems promising in relation to health improvement in asthma patients." (PMID 23091602, 2012). "Additionally, genetic polymorphisms in TLR2, TLR4, and CD14 influence susceptibility to asthma." (PMID 40718587, 2025). "Therefore, the occurrence or acute exacerbation of asthma after pathogen infection is speculated to be closely related to the TLR2-mediated mechanism." (PMID 36706056, 2023). "Therefore, we speculated that TLR2/NF-κB/NFATc1 pathway may be involved in SREBP2 regulation in asthma." (PMID 35037821, 2022). "Thus, further studies are needed to reveal the effect of TLR2 on asthma and disease severity." (PMID 33602227, 2021). "· IFN-γ-dependent prevention of experimental asthma in BALB/c offspring · A significant reduction in acetylation levels of histone 4 of the Il4 promoter after OVA challenge · The preventive effect was completely abolished in heterozygous offspring of A. lwoffii F78-treated Tlr2/3/4/7/9−/− dam." (PMID 31507589, 2019). "To explore if the recruited inflammatory monocytes could be regulated by TLR signaling and if this effect could affect subsequent asthma disease, we treated the purified inflammatory monocytes with the TLR2 agonist Pam3CSK4 in vitro before transfer into recipient mice." (PMID 30510553, 2018). "Furthermore, in fatal asthma, elevated expression of TLR2, -3 and -4 in airways may have contributed to the acute inflammation causing asthma mortalities." (PMID 25760938, 2015). "Therefore, ligands for TLR-2 were considered to aggravate experimental asthma." (PMID 23401710, 2013). "The polymorphisms rs4696480 and rs1898830 in TLR2 and the polymorphisms rs2770150, rs10759931, rs6478317, rs10759932, and rs1927911 in TLR4 increased the effect of fine particulate matter exposure on the prevalence of doctor-diagnosed asthma from birth up to eight years of age." (PMID 23496969, 2013). "Indeed, recent report has provided strong evidence that TLR2 and TLR8 may confer susceptibility to asthma and related atopic disorders." (PMID 22272212, 2012).
asthma (continued). "HDM allergens also engage TLR2 in dendritic cells to upregulate c-kit and costimulatory molecules (CD80/CD86), thereby polarizing Th2 responses and exacerbating asthma." (PMID 40529570, 2025). "Accordingly, it has been shown that in asthma and COPD, increased TF expression leads to TLR2 activation and, ultimately, inflammation." (PMID 38018577, 2023). "Compared with the control group, TLR2/TLR4 expression in the lung and duodenum tissues of OVA-induced murine asthma model was increased." (PMID 35911120, 2022). "Some TLR agonists decrease Th2 responses and relieve allergic diseases; for instance, TLR2 and TLR4 agonists can alleviate asthma symptoms." (PMID 35484967, 2022). "Toll-like receptor 2 (TLR2) is suggested to initiate the activation of NLRP3 inflammasome, and considered to be involved in asthma." (PMID 32117301, 2020). "Here, based on the data of asthma-protecting TLR-haplotypes, we investigated the intratracheal application of combinations of chemically modified Tlr1, Tlr2 and Tlr6 mRNA in a House Dust Mite (HDM)-induced mouse model of asthma." (PMID 27101288, 2016). "Only two children (8%) with wild genotypes in the TLR1, TLR2 and TLR6 genes had asthma during the first six years of life, compared to 30% in those with variant genotypes." (PMID 26741133, 2016). "In particular, TLR2 and TLR4 are regarded as the major TLRs responsible for sustaining the inflammatory responses in both asthma and COPD." (PMID 26617525, 2015). "In a mouse model, TLR2 activation of neutrophils led to the release of MMP9, which was protective against experimentally-induced asthma." (PMID 24983946, 2014). "Nevertheless, a recent study has been reported that application of TLR2, TLR3, TLR4 and TLR7 agonists all show a protective effect for asthma." (PMID 21364926, 2011). "TLR2 and TLR4 are mostly expressed by immune cells and lung epithelial cells and have major implications in the pathogenesis of chronic lung diseases such as COPD and asthma." (PMID 40468357, 2025). "In an asthma model, NAP inhibited the Th2 immune response, but did not significantly suppress asthma after Tlr2 knockdown." (PMID 39564136, 2024). "TLR2 and TLR4 are involved in the progression of asthma and type 2 diabetes mellitus (T2DM)." (PMID 36836906, 2023). "Of these receptors, TLR2 and TLR7 play an important role in the pathogenesis of asthma." (PMID 36636604, 2023). "Moreover, sputum analysis shows increased toll-like receptors (TLRs), such as TLR2 and TLR4, and several pro-inflammatory cytokines driving T2-low asthma pathobiology." (PMID 37189844, 2023). "On the one hand, TLR2 and TLR4 are involved in the progression of asthma and T2DM." (PMID 36836906, 2023). "According to many recent studies, TLR2 plays an important role in allergic diseases, such as asthma; however, its mechanism has not been fully revealed." (PMID 36706056, 2023). "We explored whether the administration of Lactobacillus fermentum CECT5716 could reduce the TLR2/TLR4 expression, inhibit the production of inflammatory factors by inflammatory cells, decrease intestinal leakage and pneumonia, and treat asthma." (PMID 35911120, 2022). "The TLR2/TLR4 expression may affect the secretion of inflammatory factors by the inflammatory cells, which regulate the target of asthma progression." (PMID 35911120, 2022). "B7-H3 also participated in the progression of asthma and augmented the inflammatory response independent of the Toll-like receptor 2 (TLR2) pathways." (PMID 32787907, 2020). "In accordance with our data, sIL-6R generation and therefore IL-6 trans-signaling in a murine model of acute experimental asthma was dependent on TLR2, but not TLR440." (PMID 31086276, 2019). "OVA-IgE, IL-4, IL-5, IL-13 and INF-gamma in BALF was also increased in TLR2-deficient mice treated with B7-H3, which suggest in OVA-induced asthma model B7-H3 augment the inflammatory response independent of TLR2 pathway." (PMID 28094276, 2017).
asthma (continued). "We did not observe any association between TLR2, TLR4 or CD14 SNPs and asthma onset, nor was there any modification of these relationships by childhood farm exposure/childhood rural environment." (PMID 28262750, 2017). "Since KSpn, targets both TLR2 and TLR4, it may have increased potential for effective suppression of asthma, and S. pneumonia components or vaccines, may have applicability as human therapies." (PMID 27309732, 2016). "Another cell surface TLRs agonist is Pam3CSK4 that acts as a synthetic TLR2 agonist and exhibits antiasthmatic effects by reducing Th2 cytokine release, AHR, IgE levels, airway inflammation, and asthmatic symptoms in animal models of asthma." (PMID 27274620, 2016). "For TLR2 and TLR4 expression at 9 h is also significantly higher in asthma than in ABPA." (PMID 27708669, 2016). "Since TLR2 and TLR4 are important in innate immunity and asthma, and recognize components of S. pneumoniae, we hypothesized that these receptors play an important role in the development of AAD and S. pneumoniae-mediated suppression of AAD." (PMID 27309732, 2016). "The TLR2 SNP, +399A/G and TLR2 -16934 SNP (in males) also presented an interaction with asthma, but it was not considered important since the previous analysis did not reveal any significant associations." (PMID 27495363, 2016). "Some have shown that TLR2 and TLR4 agonists may be beneficial in asthma, whereas others show that some TLR4 agonists such as lipopolysaccharide (LPS) exacerbate disease." (PMID 27309732, 2016). "Expression of TLR2 and TLR4 as well as that of the pro-inflammatory cytokines IL-8 and IL-1 increased in subjects with neutrophilic asthma as compared with that in other asthma subtypes and controls." (PMID 25760938, 2015). "There was no relation between TLR2 rs5743708 or TLR4 rs4986790 on asthma ever when Eastern or Western environment was taken into account." (PMID 23496969, 2013). "The engagement of TLR2 and TLR4 molecules during house dust mite sensitization leads to an asthma phenotype dominated by neutrophils and TH17 cells, a clinical feature that represent a more severe asthma." (PMID 23805294, 2013). "On the other hand, interactions of TLR2, CD14 genotype, with farm exposure, and/or endotoxin exposure may protect against the the development of asthma." (PMID 22272211, 2012). "Furthermore, many studies, including a study from 2017, reported that TLR2 plays an important role in allergic diseases, such as asthma; however, the mechanism has not been fully elucidated." (PMID 36706056, 2023). "However, the TLR4 agonist lipopolysaccharide (LPS) induces TLR4 expression rather than that of TLR2 and results in elicitation of asthma." (PMID 35484967, 2022). "TLR2 and TLR4 are expressed by DCs, macrophages, neutrophils, the airway epithelium and some subsets of Tregs, which implicates these cells in many processes that may be manipulated in TLR-directed therapies for AAD/asthma." (PMID 27309732, 2016). "TLR2 and TLR4 are expressed by DCs, macrophages, neutrophils, the airway epithelium and some subsets of Tregs, which implicates them in many cellular processes that may be manipulated in TLR-directed therapies for AAD/asthma." (PMID 27309732, 2016). "A multitude of studies demonstrate that TLR2 stimulation with systemic or mucosal administration of synthetic agonists can prevent antigen presenting cells from eliciting a TH2-polarized response, thereby reducing IgE antibodies and allergenicity in murine asthma models." (PMID 25309051, 2014). "Therefore in our study the protective effects of KSpn in AAD may not be as pronounced in TLR2-/- mice, because a lack of stimulation of the epithelium that is known to contribute to inflammatory responses in asthma." (PMID 27309732, 2016). "The involvement of TLR2, TLR4 and MyD88 in the pathogenesis of AAD and asthma is incompletely understood, and has not been studied in S. pneumoniae-mediated suppression of AAD." (PMID 27309732, 2016).
asthma (continued). "Additionally, genetic variations in TLR2, but not in TLR4, seem to sign responsible for an observed protection of farmers' children from allergy and asthma." (PMID 18315836, 2008).
viral infection (104 papers, 2009 to 2026). "During the viral infection, membrane-associated proteins interaction with TLR2 and TLR4 plays a nuanced role in exceeding inflammatory responses via adhesion and invasion that vitiate the host cell (Olejnik, Hume & Muhlberger, 2018)." (PMID 33828922, 2021). "Thus, TLR2 activation became a potential hallmark for reconstruction of CD8+ T cell activity for treatment of viral infection and cancer." (PMID 34620075, 2021). "To determine if the increased susceptibility to viral infection of the IL-21R KO mice could be due to an inherent altered expression of PRRs we measured mRNA levels of TLR2, TLR3, TLR9, MDA-5, AIM-2, DAI, RIG-I and IFI16." (PMID 24358128, 2013). "Additionally, TLR2 polymorphisms have been studied in the context of viral infections." (PMID 41295183, 2025). "To study this, we used the E protein from SARS-CoV-2, which has been described to be the mediator of inflammation during this viral infection in a TLR2-dependent pathway." (PMID 40067393, 2025). "The Toll-like receptor 2 (TLR2) pathway is crucial for B cell activation and innate immunity following bacterial and viral infections." (PMID 40724870, 2025). "Given that the protein level of MyD88 expression remains unaltered following HSV-1 infection, viral infection leads to an elevation in the mRNA levels of TLR2 and TLR3, an effect that can be mitigated by PVE30." (PMID 38185640, 2024). "First- miR-150 - regulates the expression level of TLR2, a receptor involved in the primary mechanism of the immune response that protects against bacterial and viral infections." (PMID 38085380, 2023). "A protective factor seems to be the expression of TLR-2, which was found to be higher in female mice augmenting resistance against viral infections (especially coxsackie virus)." (PMID 37511278, 2023). "In comparison with the control group, remarkable up-regulation of TLR2 transcripts was observed at 2–7 dpi in the brain and gill after viral infection, reaching a peak value of the control group at 3 dpi (3.58-fold) and 4 dpi (5.95-fold), respectively." (PMID 38003793, 2023). "qRT-PCR analyzed the immune genes, including IL-1β, TRAF3, TNF-α, and TLR2 expression levels in JFSP cells after virus infection." (PMID 36552207, 2022). "In general, the activation of both MyD88 and NF-κB is essential for TLR2-mediated inflammatory responses following viral infection." (PMID 36171749, 2022). "There is evidence that human mast cells can constitute a persistent viral infection reservoir as mast cell exposure to TLR2 (toll-like receptors), −4, or −9 ligands can trigger virus replication in latently infected cells." (PMID 34440163, 2021). "TLR2 signaling on NK cells has been shown to induce NK cell activation, a mechanism that can play a critical role in the control of viral infections such as vaccinia virus or herpes simplex virus." (PMID 33522421, 2021). "Being a sensor for lipopeptides and lipoproteins, TLR2 plays a critical role in host defense against many bacterial and viral infections." (PMID 34866574, 2021). "TLR2, as part of the innate immune response, has been connected to antiviral action against multiple viral infections." (PMID 33224264, 2020). "Other studies have reported that direct TLR2 engagement is important for NK cell activation, including during the response to virus infections (e.g. vaccinia and herpes simplex virus) or ligands such as the protein‐bound polysaccharide krestin." (PMID 32696994, 2020). "The identification of critical roles of CLEC2 and CLEC5A/TLR2 in platelet-leukocyte interactions will support the development of novel strategies to treat acute viral infection in the future." (PMID 31160588, 2019). "As a consequence, they have lower capacity to recognize and combat pathogens, since TLR2 is fundamental in the immune response against many bacterial, fungal, and viral infections." (PMID 30692998, 2018).
viral infection (continued). "Along with other receptors of innate immunity, TLR2 has been reported to shape the adaptive immune response in different animal models of viral infection." (PMID 30254622, 2018). "As the response of these cytokines occurs early during a viral infection, their mRNA levels were down regulated in the lungs of TLR2/9−/− mice in the first hours after intranasal infection." (PMID 28222752, 2017). "In this review, we discuss the role of TLR2 in recognizing viral pathogens, and highlight the function of soluble TLR2 (sTLR2) in the regulation of the immune response to bacterial and viral infection, as well as the various implications." (PMID 27531999, 2016). "TLR2 itself is down-regulated at the transcriptional level during HSV2 infection, underlining the importance of this innate immune sensor to control viral infection." (PMID 25955717, 2015). "TLR-3 is known to play a key role in the host response to virus infection by detecting virus-derived dsRNA in intracellular vesicles, whereas TLR-2 and TLR-4 recognise viral structural proteins on the plasma membrane." (PMID 25973612, 2015). "Strikingly, in contrast with WT virus infection in which TLR2 level decreased over time, TLR2 levels remained stable 3 and 5 days post-infection with the miR-UL112-3p-deficient virus." (PMID 25955717, 2015). "In fact, it is now known that one of the most effective vaccines, the live-attenuated yellow fever vaccine, activates multiple DC subsets through TLR2, TLR7/8 and TLR9, which leads to a robust balanced immune response." (PMID 26344621, 2014). "ICP0 plays a key role in blocking IFN-induced inhibition of viral infection as well as the TLR2/TLR9-mediated inflammatory cytokine response to HSV infection." (PMID 24979708, 2014). "Given that the primary function of IFN-β is in antiviral defense, we next examined the effect of TLR2 priming on the course of a model virus infection." (PMID 23853595, 2013). "TLR2, 4, and 5 are the primary sensors of bacteria, and crosstalk occurs between other toll-like receptors that respond to viral infection." (PMID 22567325, 2011). "Other laboratories have shown that TLR2-/- mice are less susceptible to HSV-1, showing lower mortality rates following viral infection." (PMID 20584314, 2010). "Using a murine model of herpes simplex virus (HSV)-1 encephalitis, our laboratory has determined that induction of proinflammatory mediators in response to viral infection is largely mediated through a Toll-like receptor-2 (TLR2)-dependent mechanism." (PMID 20584314, 2010). "Stimulation with HSV-1 elevated intracellular ROS in wild-type microglial cell cultures, while TLR2-/- microglia displayed delayed and attenuated ROS production following viral infection." (PMID 20584314, 2010). "To corroborate the role played by TLR2/4 triggering in late virus transfer, we measured the effect of TLR2 and 4 ligands upon acute virus infection of IM-MDDCs." (PMID 19419540, 2009). "TLR2 and 4 reside on cell surface plasma membranes but may also play a role in viral infections through the recognition of viral proteins." (PMID 38257841, 2024). "A study demonstrated the participation of TLR2 in the activation of memory T CD8+ cells, during an established chronic viral infection in a murine model, causing an increase in the proliferation and expansion of these cells, induced by IL-7 both in vitro and in vivo." (PMID 38203441, 2023). "Moreover, US3 can also act as an inhibitor of NF-κB signaling by reducing the polyubiquitination of TRAF6 through its kinase activity and inhibiting Toll-like receptor 2 (TLR2) signaling at the early stage of viral infection." (PMID 35196784, 2022). "In addition, the expression of four immune-related genes, TRAF3, IL-1β, TNF-α, and TLR2, was differentially altered following viral infection." (PMID 36552207, 2022). "There is increasing evidence of TLR2 involvement in responses to viral infections." (PMID 33522421, 2021).